ITGA5 (integrin subunit alpha 5)
Diseases named in the same sentence as ITGA5 in open-access papers (continued):
Sharing a sentence is not in itself a finding about the gene and the disease.
colorectal cancer (23 papers, 2018 to 2025). A primary or metastatic malignant neoplasm that affects the colon or rectum. "It has been shown that overexpression of ITGA5 is closely associated with enhanced O-GlcNAcylation, accelerating the progression of colorectal cancer." (PMID 36267977, 2022). "Numerous studies have shown that the overexpression of ITGA5 is linked to unfavorable outcomes in various types of tumors, including triple-negative breast cancer, ovarian cancer, colorectal cancer and lung cancer." (PMID 38903179, 2024). "In this study, we explored the prognostic impacts of HIF-1α, LOX and ITGA5 expression in the tumor microenvironment and their relationship with KRAS/NRAS/BRAF mutation status in colorectal cancers." (PMID 39857068, 2025). "In line with this, FN1 has been shown to promote colorectal cancer progression by enhancing cell viability, invasion, and migration through interaction with ITGA5." (PMID 40860666, 2025). "Targeting ITGA5 in fibroblasts through alternation of extracellular matrix (ECM) deposition can improving colorectal cancer response to PD-L1 blockade." (PMID 38903179, 2024). "The interaction of this compound with ITGA5 was found to inhibit apoptosis while promoting viability, invasion, and migration in colorectal cancer." (PMID 38216996, 2024). "For example, ITGA5 has been shown to ptomote the occurrence and development of colorectal cancer, SLC2A3 can promote macrophage infiltration by glycolysis reprogramming in gastric cancer." (PMID 36959648, 2023). "The involvement of ITGA5 in miRNA-based modulation has been validated in diverse malignancies, including colorectal cancer, glioblastoma and bladder cancer." (PMID 36765401, 2023). "For instance, the expression of ITGA5 is elevated in colorectal cancer tissues and cells and this elevation can enhance colorectal cancer cell growth and tumorigenesis while decreasing cell apoptosis." (PMID 36765401, 2023). "FN1 interacted with binding partner ITGA5 and promoted viability, invasion, and migration in colorectal cancer through suppressing apoptosis." (PMID 36212151, 2022). "We previously showed the strong upregulation of ITGA5 in Caco-2 human colorectal cancer cell lines exposed to hypoxia, as a consequence of hypoxia-induced decrease in expression of its direct regulator—miR-148a." (PMID 34938324, 2021). "ITGA5 is highly expressed in oral squamous cell carcinoma, pancreatic cancer, GC, and colorectal cancer, and its high expression is negatively correlated with patient OS." (PMID 33335550, 2020). "Next, we analyzed expression correlation for these transcription factors, ITGA5, and PLAUR in the mRNA-sequencing data of colorectal cancer samples from TCGA to find regulators which expression significantly correlates with both ITGA5 and PLAUR in the samples of intestinal origin." (PMID 34858489, 2021). "Prior research demonstrated that hypoxia downregulation of hsa-miR-148a-3p led to the overexpression of its two target genes, ITGA5 and PRNP, which was a factor in colorectal cancer patients’ tumor development and poor prognosis." (PMID 36110217, 2022). "Analysis of correlation of all detected transcription factors with ITGA5 and PLAUR in the colorectal cancer samples from TCGA revealed six genes with significant correlation." (PMID 34858489, 2021). "IHC confirmed low expression of ITGA5 and PIGK in colorectal cancer." (PMID 36405728, 2022). "Several studies have reported that FN1 modulates cell behaviour through interaction with integrin ITGA5 and activation of PI3K/AKT signalling, which results in the suppression of apoptosis and increase in the viability, invasion, and migration of colorectal cancer cells." (PMID 32228629, 2020).
ovarian carcinoma (23 papers, 2012 to 2025). A malignant neoplasm originating from the surface ovarian epithelium. "Amongst this group of genes, ITGA5 (up-regulated) encodes for the alpha 5 subunit of the alpha-5/beta-1 integrin that associates with RAB25 to promote invasive migration of ovarian carcinoma cells." (PMID 22724020, 2012). "A similar result was confirmed by a recent study by Hussain and colleagues, in which they demonstrated that ITGA5 can be used as a new CAF marker in ovarian cancers." (PMID 36831470, 2023). "Other studies report that expression of ITGA5 is increased in breast and ovarian cancers compared to normal tissue." (PMID 38248716, 2023). "Studies have confirmed that ITGA5 is highly expressed in gastric, breast, and ovarian cancer, which can be used as a prognostic tumor marker and is closely related to the adverse prognosis of patients." (PMID 36742137, 2023). "Previous study showed that cancer-associated fibroblasts recruit ITGA5 high HGSOC ascitic tumor cells to form metastatic units, suggesting the potential biologic regulatory mechanism of ITGA5 in ovarian cancer." (PMID 36585688, 2022). "The high expression of ITGA5 was significantly related to poor prognosis in patients with peritoneal metastasis of ovarian cancer, and the OS time of patients with advanced ovarian cancer and with high ITGA5 expression was relatively shorter." (PMID 33335550, 2020). "Using the linear combination of IGSF8 and ITGA5 on the ovarian cancer (n = 10) and healthy control samples (n = 20) on this specificity data set, we achieved a PPV of 15.3% with a sensitivity of 0.90 at specificity of 99.8%, confirming the reliability of our original marker set." (PMID 37884576, 2023). "For example, miR-17 suppresses peritoneal metastasis in ovarian cancer through ITGA5 and ITGB1." (PMID 33024414, 2020). "Despite not knowing all of the functions performed by ITGA5, multiple studies have demonstrated that increased expression of ITGA5 is associated with poor prognosis in multiple tumors types, such as triple negative breast cancer, lung cancer, hepatocellular carcinoma and ovarian cancer." (PMID 33711961, 2021). "In these ovarian cancer cells, FN-adhesion was dependent on ITGA5/B1, but independent of ENTPD5, suggesting potential tissue- or cell type-specific requirements for ENTPD5 in integrin folding." (PMID 37563605, 2023). "In ovarian cancer, FOXM1 also induces the expression of integrins and matrix proteins: ITGB1, ITGAV, ITGA5, LMNB1, and FN1, which may facilitate adhesion of ovarian cancer cells to new organs." (PMID 34205406, 2021). "Here, we designed small-scale siRNA screens targeting these six mesenchymal signature genes (CD99L2, EMP3, ITGA5, SYDE1, VIM, ZEB1) to explore their functional relevance and their roles during EMT reversal by nintedanib (BIBF1120) in a mesenchymal-like SKOV3 ovarian cancer cell line." (PMID 26061747, 2015). "Similarly, the cohorts (GSE26712) showed that high ITGA5 expression levels were correlated with poor prognosis (OS HR = 1.58, 95% CI = 1.06 to 2.36, Cox P = 0.025; DFS HR = 1.54, 95% CI = 1.06 to 2.24, Cox P = 0.025) in ovarian cancers." (PMID 33711961, 2021). "Expression of ITGA5 and ITGB1 inversely correlated with disease-free survival in pancreatic, but not breast, lung, or ovarian cancer." (PMID 37563605, 2023). "We observed in this independent set of samples that FOLR1, ITGB3, ITGA5 and ACSL4 have higher expression for majority of the ovarian cancer cases compared to the non-ovarian cases." (PMID 37884576, 2023).
gastric cancer (17 papers, 2013 to 2025). A primary or metastatic malignant neoplasm involving the stomach. "For instance, ITGA5 has been implicated in the tumor-suppressive effects of miR-31 on gastric cancer as a target gene to repress tumor cell invasion and metastasis." (PMID 36765401, 2023). "The current study showed that the children of GCA, who are at a high risk of gastric cancer, can express with a 5-fold higher risk to be ITGA5-1160/ITGB1-1949/ITGB1 + 31804 as T/A/C carriers in ITGA5 and ITGB1 than DU." (PMID 25884934, 2015). "ITGA5 is significantly expressed in gastric cancer stem cells, and its elevated expression correlates with reduced survival rates in gastric cancer patients." (PMID 40710326, 2025). "Targeting ITGA5 can weaken the tumor sphere formation ability of gastric cancer stem cells and suppress the stem-like characteristics of gastric cancer." (PMID 39239559, 2024). "These DEGs were then intersected with the top 10 known genes related to gastric cancer obtained from the MalaCards database, with ITGA5 identified." (PMID 36765401, 2023). "ITGA5 was elevated in gastric cancer tissues and confirmed as a target gene of the miR-148/152 family members." (PMID 36765401, 2023). "Increase of ITGA5 acts importantly in the development of gastric cancer and is considered as a potential therapeutic target and biomarker." (PMID 36765401, 2023). "ITGA5 had abundant existence in gastric cancer, and its upregulation correlated with the survival prognosis of patients." (PMID 36742137, 2023). "In brief, low expression of the miR-148/152 family members was detected in the gastric cancer tissues and cells and the miR-148/152 family can target ITGA5 gene." (PMID 36765401, 2023). "The mRNA levels of AKR1B10 and integrin subunit alpha 5 (ITGA5) in gastric cancer tissues and cell lines were measured by real-time quantitative polymerase chain reaction." (PMID 37823316, 2023). "In our previous study, bioinformatics analysis showed that the expression of ITGA5 was significantly increased in gastric cancer, and miR-148/152 family members all had targeted binding sites with ITGA5." (PMID 36765401, 2023). "Our experimental data evinced that the miR-148/152 family members exerted anti-tumor actions by suppressing colony formation, self-renewal and migrative properties, and drug resistance of gastric cancer stem cells through inhibition of ITGA5." (PMID 36765401, 2023). "Overall, the miR-148/152 family members exerted inhibitory effects on the tumorigenesis in vivo of gastric cancer stem cells by downregulating ITGA5." (PMID 36765401, 2023). "Via rescue experiments, it was concluded that AKR1B10 served as tumor suppressor potentially by ITGA5 expression in gastric cancer." (PMID 37823316, 2023). "More importantly, ITGA5 has been characterized to be upregulated in gastric cancer, and its high expression indicates the poorer survival of patients with gastric cancer." (PMID 36765401, 2023). "As revealed in our study, ITGA5 was targeted by the miR-148/152 family and attenuated the antitumor potential of miR-148/152 family against gastric cancer." (PMID 36765401, 2023). "In gastric cancer, target suppression of ITGA5 resulted in a great reduction in the invasive and migrative abilities of gastric cancer cells." (PMID 36742137, 2023). "Our results indicated that AKR1B10 inhibited migration, invasion, and adhesion of gastric cancer cells via modulation of ITGA5." (PMID 37823316, 2023). "Nonetheless, the possible effect of ITGA5 on the gastric cancer stem-cell like properties remains elusive." (PMID 36765401, 2023). "The effect of overexpression of ITGA5 on tumor progression was examined, and the live images showed the successful construction of the nude mouse transplantation tumor model for gastric cancer." (PMID 36193075, 2022). "The effect of ITGA5 on gastric cancer cells was examined by in vivo and ex vivo experiments, so as to understand its role." (PMID 36193075, 2022).
gastric cancer (continued). "A total of 10 pairs of gastric cancer sequencing samples showed a significantly higher ITGA5 mRNA expression compared to the expression in the corresponding paracancerous normal tissues." (PMID 36193075, 2022). "Subsequently, the expression of ITGA5 in gastric cancer tissues was confirmed by qRT-qPCR and Western blot, and the results showed that ITGA5 was significantly higher in gastric cancer tissues than in the adjacent normal tissues." (PMID 36193075, 2022). "ITGA5 protein expression was significantly increased in gastric cancer tissues from patients, as revealed by tissue immunofluorescence, and ITGA5 was mainly expressed on the cell membrane." (PMID 36193075, 2022). "Our results finally showed that the effect of ITGA5 on proliferation, invasion, and migration of gastric cancer cells was performed through the activation of the FAK/AKT pathway." (PMID 36193075, 2022). "In vitro and in vivo experiments showed that ITGA5 silencing resulted in the inhibition of proliferation, invasion, migration, and graft growth of gastric cancer cells; conversely, the overexpression resulted in the promotion of these cell functions." (PMID 36193075, 2022). "AGS stable-transformed cells were inoculated into nude mice to construct a nude mouse tumor model to further verify in vivo the role of ITGA5 in gastric cancer." (PMID 36193075, 2022). "In contrast, ITGA5 overexpression significantly increased the proliferation and clone formation of gastric cancer cells." (PMID 36193075, 2022). "ITGA5 expression was increased in gastric cancer patients with larger tumors compared with smaller tumors (P < 0.05)." (PMID 36193075, 2022). "The expression of ITGA5 in gastric cancer tissues was assessed by the use of molecular bioinformatics databases and high-throughput sequencing of gastric cancer tissues from patients." (PMID 36193075, 2022). "Transwell invasion and migration assays showed that ITGA5 gene silencing significantly decreased the invasion and migration ability of gastric cancer cells." (PMID 36193075, 2022). "Western blot, qPCR, and immunohistochemistry were performed to detect the expression of ITGA5 in samples from gastric cancer patients and gastric cancer cell lines." (PMID 36193075, 2022). "ITGA5 mRNA and protein expression were upregulated in gastric cancer cell lines and tissues from patients, and its expression was closely associated with tumor size, lymph node metastasis, and TNM stage." (PMID 36193075, 2022). "Further confirmation in gastric cancer cell lines revealed that ITGA5 was also highly expressed in all these cells." (PMID 36193075, 2022). "AGS and MKN-28, 2 gastric cancer cell lines with relatively high ITGA5 expression, were selected for this experiment to further understand the biological function of ITGA5 in gastric cancer." (PMID 36193075, 2022). "In conclusion, our results indicate that ITGA5 is highly expressed in human gastric cancer and cell lines and has protumorigenic effects." (PMID 36193075, 2022). "ITGA5 gene regulates the proliferation, invasion and migration of gastric cancer cells through the phosphorylation of FAK and AKT, being a potential biomarker." (PMID 36193075, 2022). "The results showed that ITGA5 is an oncogene in gastric cancer, allowing the progression of gastric cancer by the activation of the FAK/AKT signaling pathway." (PMID 36193075, 2022). "This study revealed that ITGA5 was significantly upregulated in gastric cancer tissues of patients, and its expression was negatively correlated with patient survival." (PMID 36193075, 2022). "ITGA5 expression was the highest among the significantly differentially expressed integrin genes and was significantly highly expressed in gastric cancer tissues." (PMID 36193075, 2022).
gastric cancer (continued). "Next, the expression of ITGA5 mRNA and protein in gastric cancer cell lines was examined, resulting in a higher expression in all the three gastric cancer cell lines than in the Ges-1 cells, with a higher expression in AGS and MKN28 cells." (PMID 36193075, 2022). "ITGA5 expression was significantly increased in advanced gastric cancer compared with early gastric cancer (P < 0.05)." (PMID 36193075, 2022). "CCK-8 and clone formation assays showed that ITGA5 silencing significantly inhibited the proliferation and clone formation of gastric cancer cells." (PMID 36193075, 2022). "Results from IHC staining and western blot further proved that markers of Th2 and M2 cell were significantly increased in gastric cancer patients with high ITGA5 expression levels." (PMID 33711961, 2021). "High expression of ITGA5 was correlated with poor prognosis in gastric cancer stages II-IV, T2-T4, N1-N3 and M0-M1." (PMID 33711961, 2021). "There were genomic predispositions of SNPs in the ITGA5, ITGB1, IL-10 and COX-2 genes in the children of GCA, who are considered to be a risk group of gastric cancer after H. pylori infection." (PMID 25884934, 2015). "ITGA5 is significantly upregulated in CD44+EpCAM + gastric cancer stem cells." (PMID 39239559, 2024). "We then explore the effect of ITGA5 on gastric cancer stem cells." (PMID 36765401, 2023). "ITGA5 was observed to be elevated in gastric cancer tissues and cells." (PMID 36765401, 2023). "This study demonstrates that the miR-148/152 family members may prevent gastric cancer stem cell-like properties by targeting ITGA5, which can serve as an appealing target for gastric cancer treatment." (PMID 36765401, 2023). "Following Western blot analysis, we found a high level of ITGA5 in gastric cancer tissues." (PMID 36765401, 2023). "In summary, the current study detailed the anti-carcinogenic action of the miR-148/152 family members in gastric cancer development through its interplay with ITGA5, thus offering a novel therapeutic target for developing effective treatment modalities against gastric cancer." (PMID 36765401, 2023). "Furthermore, the ITGA5 gene was silenced and overexpressed in gastric cancer cells, and the effect on proliferation, invasion, migration, and tumorigenic ability was assessed." (PMID 36193075, 2022). "Therefore, the aim of this study was to investigate the role of ITGA5 in gastric cancer, focusing on the mechanism regulating the proliferation, invasion and migration." (PMID 36193075, 2022). "However, the available information regarding ITGA5 in gastric cancer is poor, and the relationship between ITGA5 and gastric cancer is still unclear." (PMID 36193075, 2022). "Interestingly, immune markers for monocytes, tumor - associated macrophages (TAMs), macrophages 2 (M2) cells and T-helper 2 (Th2) cells were found to be significantly and positively correlated with ITGA5 expression levels in colon and gastric cancer." (PMID 33711961, 2021). "The comparison of ITGA5 expression in 40 pairs of gastric cancer tissues with the paired paraneoplastic tissues detected by immunohistochemistry revealed that ITGA5 expression was significantly increased in gastric cancer tissues compared with the paired paraneoplastic tissues (P < 0.05)." (PMID 36193075, 2022). "However, the role of ITGA5 in gastric cancer is unclear, thus requiring a more in-depth study." (PMID 36193075, 2022). "Thus, ITGA5 promoted gastric cancer progression by activating the FAK/AKT pathway." (PMID 36193075, 2022). "Similarly, high expression levels of ITGA5 were associated with worse PFS in stage II through IV gastric cancer patients (P < 0.05) but not in stage I gastric cancer patients." (PMID 33711961, 2021). "ITGA5 promotes tumor progression through the FAK/AKT pathway and mediates cancer cell–fibroblast adhesion and peritoneal dissemination in gastric cancer." (PMID 39099892, 2024).